HLA-B (major histocompatibility complex, class I, B)
Diseases named in the same sentence as HLA-B in open-access papers (continued):
Sharing a sentence is not in itself a finding about the gene and the disease.
narcolepsy (1 paper, 2019). A sleep disorder characterized by a tendency for excessive sleepiness during the day which occurs even after adequate sleep in the nighttime. "The HLA-I molecules were chosen based on reported associations with narcolepsy in two independent studies, i.e., HLA-A*11:01, HLA-B*18:01, B*35:01, B*51:01, and HLA-C*04:01." (PMID 30783092, 2019).
non-small cell lung carcinoma (1 paper, 2021). A group of at least three distinct histological types of lung cancer, including non-small cell squamous cell carcinoma, adenocarcinoma, and large cell carcinoma. "The NCI-H1299 (human non-small cell lung carcinoma cell line) cells (HLAA*2402, 3201; HLAB*4002, 4002) were used for the transfection of the two subtypes of HLA-B27, with the GFP fused to the C-terminus of each subtype." (PMID 35082784, 2021).
oral cancer (1 paper, 2023). "Fifteen variants on chromosome 6p21 were associated with oral cancer with genome-wide significance (p < 5 × 10−8), twelve of which were highly linked and located in or near the HLA-B gene on 6p21.33." (PMID 36769103, 2023).
oropharyngeal cancers (1 paper, 2018). Carcinoma, predominantly squamous cell, arising from the epithelial cells of the oropharynx. "Interestingly, IL3RA, HLA-A and HLA-B have copy number gains in HPV positive oropharyngeal cancers." (PMID 29879932, 2018).
panic disorder (1 paper, 2022). An anxiety disorder characterized by multiple unexpected panic attacks with persistent concern of recurring attacks. "HLA-B and HLA-DRB1 were investigated as candidate susceptibility genes for panic disorder in 744 subjects and 1418 control subjects." (PMID 36231907, 2022).
pars planitis (1 paper, 2023). An inflammatory disorder of the cilliary body in the uvea that affects healthy, younger individuals who are often asymptomatic. "The HLA-B*51 was more frequent in patients with pars planitis, often accompanying MS." (PMID 36768413, 2023).
Plasmodium falciparum malaria (1 paper, 2020). Malaria resulting from infection by Plasmodium falciparum. "Noteworthy is the fact that particular HLA-B alleles have been positively selected in African human populations in response to Plasmodium falciparum malaria and that functionally similar alleles have recently been identified in bonobos which live in an area with a high prevalence of this parasite." (PMID 32933484, 2020).
pneumonia (1 paper, 2025). An acute, acute and chronic, or chronic inflammation focally or diffusely affecting the lung parenchyma, caused by an infection in one or both of the lungs (by bacteria, viruses, fungi, or mycoplasma.). "ICI-related pneumonia is associated with the expression of HLA-B*35 and/or DRB1*11 alleles." (PMID 41357573, 2025).
rectal cancer (1 paper, 2024). A primary or metastatic malignant neoplasm that affects the rectum. "In Antigen processing and presentation, the complex of B2M and HLA-B/C activates down-stream signals, upregulates and enhances T cell immunity, and plays an important role in controlling colon/rectal cancer growth." (PMID 38280998, 2024).
relapsing-remitting MS (1 paper, 2013). "The EBV-specific CD8+ T-cell response was studied with the pentamer technology in 43 HD and 113 patients (79 untreated and 34 treated) with relapsing-remitting MS who were selected according to their HLA genotype (HLA-A*0201 and/or HLA-B*0801)." (PMID 23592979, 2013).
renal dysfunction (1 paper, 2022). "The incidence of severe reactions is highest during the first 2 months of therapy, and is associated with advanced age, renal dysfunction, and presence of the HLA-B*5,801 variant." (PMID 36081938, 2022).
Renal insufficiency (1 paper, 2020). A reduction in the level of performance of the kidneys in areas of function comprising the concentration of urine, removal of wastes, the maintenance of electrolyte balance, homeostasis of blood pressure, and calcium metabolism. "Results still showed an impact of the HLA-B*5801 and seem robust when age or renal insufficiency are taking into account." (PMID 32746911, 2020).
Salmonella Infections (1 paper, 2022). Infections with bacteria of the genus SALMONELLA. "Furthermore, while HLA-B*27:05 has been linked to nontyphoidal Salmonella infections, this is the first study to find a potential association with enteric fever." (PMID 35254093, 2022).
serous ovarian cancer (1 paper, 2010). "Renewed analysis of the previously published data using only late-stage serous ovarian cancer patients (n=151) did not yield a correlation of HLA-B/C expression with DSS either (data not shown)." (PMID 20664601, 2010).
silicosis (1 paper, 2021). Silicosis is a respiratory disease caused by breathing in (inhaling) silica dust. "The major disease-related genes of silicosis may be mapped near the HLA-B locus." (PMID 34149803, 2021).
skin toxicity (1 paper, 2024). "HLA-B*57:01-transgenic mice also exhibited ER stress in epidermal areas following abacavir administration, and abacavir-induced skin toxicity was attenuated by the administration of 4-PB." (PMID 38628599, 2024).
Sleep disturbance (1 paper, 2025). An abnormal pattern in the quality, quantity, or characteristics of sleep. "Despite comparable disease duration and joint involvement, the HLA-B*27-positive group experienced a higher burden of sleep disturbances (31.82% vs. 14.29%) and significantly higher perceived psychological stress (mean score 2.41 vs. 1.21, p < 0.001)." (PMID 40868248, 2025).
thyroid tumor (1 paper, 2020). A benign or malignant neoplasm affecting the thyroid gland. "In HLA-B*18:01 carriers, the SAT US pattern may be highly misleading, largely resembling a large thyroid tumor." (PMID 32079059, 2020).
trachoma (1 paper, 2014). "This dependence can be explained by the presence of a common HLA-B*08∼C*03 haplotype, which we estimate to have a frequency of around 5.7% in the Gambian trachoma families." (PMID 24651768, 2014).
uremia (1 paper, 2016). A clinical syndrome associated with the retention of renal waste products or uremic toxins in the blood. "Based on the statistical analysis of 1,464 uremia patients and 10,000 unrelated healthy individuals, we detected 23 HLA-A alleles, 49 HLA-B alleles and 17 HLA-DRB1 alleles." (PMID 27780235, 2016). "Of the 49 HLA-B alleles, six alleles (B62, B54, B15, B40, B56, and B65) show significantly different frequencies in patients and healthy groups, and four of them (B62, B54, B15, and B40) show frequencies greater than 1% in uremia patients." (PMID 27780235, 2016). "In this study, genotypes of HLA-A, HLA-B and HLA-DRB1 loci were collected from 1,464 uremia patients and 10,000 unrelated healthy individuals in Henan province of China." (PMID 27780235, 2016).
urticaria (1 paper, 2025). A vascular reaction of the skin characterized by erythema and wheal formation due to localized increase of vascular permeability. "The patient with an FDR presented here had HLA-A30 B13 Cw6, HLA-B*13, and HLA DRB1*13-DQB1*06 haplotypes, which make her susceptible to an FDR induced by trimethoprim/sulfamethoxazole and dapsone, as well as to aspirin-induced urticaria, respectively." (PMID 39859393, 2025).
tumor (188 papers, 1989 to 2026). "Our findings align with the original study’s observations, as we also detected a marked reduction in HLA class I gene expression among tumor post-treatment cells, specifically showing a complete loss of both HLA-B alleles." (PMID 41229397, 2025). "Specifically, we found upregulation of genes associated with antigen presentation (HLA-A, HLA-B, and HLA-C) following tumor treatment with radiotherapy." (PMID 40858520, 2025). "The HLA-B*07:02 variant is involved in viral clearance and plays an important role in the development of antitumor cells, being associated with tumor regression." (PMID 39201523, 2024). "Only one tumor sample of CCRCC lost one allele inall HLA-A, HLA-B,and HLA-C genes, and two tumor samples of LUAD lost one allele inHLA-A and HLA-C genes." (PMID 37857377, 2023). "With all six samples taken together, we found that peptides predicted to bind to lost alleles had increased peptide intensity in tumor samples compared to normal samples for HLA-A, HLA-B and HLA-C alleles." (PMID 35414054, 2022). "Intriguingly, the expression of HLAB gene, which was also part of the HLA complex, was reportedly associated with tumor progression in CRC." (PMID 34108011, 2021). "The presence of the HLA-A-Bw4 isoform or HLA-B-Bw4-80T isoform is associated with the improved anti-tumour response to monoclonal antibody-based immunotherapy, as compared with HLA-B-Bw4-80I." (PMID 34943866, 2021). "Comparison of the pre-treatment and post-treatment tumor from the first patient revealed the transcriptional loss of HLA-B with the injection of HLA-B restricted CD8+ T cells." (PMID 34194441, 2021). "Surprisingly, patients with loss of HLA-A and/or HLA-B in their tumours had improved PFS compared to tumours expressing both HLA-A and HLA-B (1-year PFS 30.9% median PFS 4.8 months, versus 1-year PFS 5.6%, median PFS 1.8 months)." (PMID 34956172, 2021). "Three patients with mutations in recurrent tumors were presented on HLA-B*08:01 and three patients had primary tumor neoantigens predicted to be displayed on HLA-B*07:02." (PMID 33796222, 2021). "Two tumors showed a haplotype loss (HLA-A2, B44 and HLA-A2, B13) and one tumor showed a complete HLA-A (HLA-A26, -A32) loss together with one HLA-B allotype loss (HLA-B41)." (PMID 31394860, 2019). "When comparing clinical and histopathological parameters, gene expression of HLA-A, HLA-B, B2M, and HLA-DR was positively associated with age at enucleation and with the largest basal diameter of the tumor, a well-known adverse parameter." (PMID 27764126, 2016). "A high CD8+ tumor infiltration was strongly associated with clinical benefit only when the tumors retained good expression of HLA-A and HLA-B/C (p=0.004)." (PMID 26658106, 2016). "However, certain human leukocyte antigen (HLA) class I variants, such as HLA-B*07:02, correlate with immune-hot tumours in this subgroup." (PMID 41606303, 2026). "While classical HLAs, predominantly encoded by HLA-A, HLA-B, and HLA-C genes, have enjoyed extensive scrutiny for their involvement in tumor immunosurveillance, in anti-tumor immunity, and in immune escape mechanisms, the less understood area of non-classical HLAs has also garnered attention." (PMID 39766165, 2024). "Furthermore, our analysis reveals a wide range in the breadth of tumor neoantigens restricted to specific HLA alleles, ranging from 3.5% of neoantigens arising from driver genes bound by HLA-B*37:01 to 18.6% of neoantigens bound by HLA-B*83:01." (PMID 32256484, 2020). "Here we show that the structures of two distinct TCRs (TRAV4+TRAJ21+-TRBV28+TRBJ2-3+ and TRAV4+TRAJ8+-TRBV9+TRBJ2-1+), originating from a polyclonal T-cell repertoire, bind to HLA-B*07:02, presenting a 13-amino-acid-long tumour-associated peptide, NY-ESO-160–72." (PMID 29531227, 2018). "HLA-B loss was exclusive to tumor cells and undetectable by standard HLA-ABC immunohistochemistry." (PMID 30250229, 2018).
tumor (continued). "The interactome of MGAT1, resolved through mass spectrometry, identified several tumor immune-responsive proteins, including antigen-presenting proteins such as HLA-A and HLA-B, as well as CD73." (PMID 40229283, 2025). "Defects in the TAP1 gene, a component of the antigen processing machinery, and the HLA Class I genes (HLA-A, HLA-B, and HLA-C) enable tumor cells to evade immune destruction by CD8+ T cells due to impaired presentation of tumor antigens." (PMID 41295262, 2025). "Tumor cells in regions with higher CD8 + T cell infiltration displayed elevated HLA-B expression, indicated by higher histochemical score (H-scores)." (PMID 40894019, 2025). "Future studies aimed to evaluate the in vivo anti-tumor activity of EpCAM-ReTARGTPRIFNαR149A should use tumor-bearing mice engrafted with peripheral blood mononuclear cells (PBMCs) from CMV-seropositive/HLA-B*07:02-matched donors." (PMID 40243928, 2025). "Highlighting an example, we identified a self-antigen DLSRRDVSL originating from tumor-specific gene HAVCR1 and present by a common allele HLA-B*08:01, covering over 15% of the U.S. population." (PMID 40672284, 2025). "HLA‐B molecules are crucial for presenting intracellular neoplasm‐specific antigens for recognition by CD8+ T cells, activating cytotoxic T lymphocyte responses." (PMID 41316520, 2025). "We selected 13 regions and examined the correlation between the level of infiltrating CD8 + T cells and the level of HLA-B expression in tumor cells across these regions." (PMID 40894019, 2025). "GBP-1 displays relatively strong expression in infiltrating cells while exhibiting weak expression in tumor cells, which elucidates the spatial interaction pattern between HLA-B and GBP-1." (PMID 39954675, 2025). "All five clusters of tumor epithelial cells were indeed observed in AM samples by using marker genes (HLA-B for IR, SFRP1 for BR, KRT13 for ED, ODAM for TD, LAMC2 for TD, and KI67 for CC)." (PMID 38424060, 2024). "This alternative approach to scRNA-seq using the C1 Fluidigm platform also highlighted a statistically significant increase in the expression of three classical MHC-I genes—HLA-A, HLA-B, and HLA-C—in tumor T cells from plaque/tumor late-stage skin lesions." (PMID 38272918, 2024). "Classical type I HLA molecules (HLA-A, HLA-B, and HLA-C) play a critical role in the immune response against tumor cells by presenting tumor-specific antigens on the surface of cells for recognition by cytotoxic T cells." (PMID 38383447, 2024). "In terms of HLA expression, HLA-A, HLA-B, HLA-C, HLA-E, HLA-F, HLA-G, and HLA-J were significantly more highly expressed in C2 than in C1, indicating that tumour subtypes differ in the activation of immune cells." (PMID 37691922, 2023). "An effective anti-tumor immune response requires antigen presentation, in which MHC class 1 molecules, such as HLA-A, HLA-B, and HLA-C, present antigenic peptides from tumor cells or DC to CD8 T cells." (PMID 37884639, 2023). "The expression of class I HLA molecules, which are responsible for antigen presentation to tumor-killing T-cells, including HLA-A, HLA-B, HLA-C, HLA-E, HLA-F, and B2M, was downregulated in 7, 8, 5, 10, 5, and 14 patients, respectively." (PMID 37152992, 2023). "Search settings were as follows: Dataset: Adult and CCGA, Tumor type: Primary, Gene: HLA-A, HLA-B, and HLA-C, Histology: GBM, Subtype: All, Gender: All, IDH status: Wild-type, Cutoff: Median." (PMID 37382632, 2023). "We also observed that many of the high-DAI neo-epitopes on all tumor types were constituted preferentially with HLA-A and HLA-B over HLA-C." (PMID 37427594, 2023).
tumor (continued). "The results indicated that urolithin B prevents colorectal carcinogenesis by remodeling gut microbial and tumor immune microenvironments, such as HLA-B, NK cells, regulatory T cells, and γδ TCR cells, and decreasing the PD-L1." (PMID 36778211, 2023). "The cumulative HLA allele frequency coverage per tumor type or subtype in the corresponding PDX models ranged from 0.40 to 0.96 for HLA-A, from 0.27 to 0.80 for HLA-B, and from 0.23 to 0.97 for HLA-C." (PMID 37723198, 2023). "Since NK cells are sensitive to cells with decreased expression of HLA-I, the strength of interaction of KIR3DL1 and HLA-B subtypes determines the degree of NK inhibition and hence their anti-tumor activities." (PMID 37647275, 2023). "By contrast, only three tumors (one individual) demonstrated methylation at HLA-B, and only one tumor had HLA-C or B2M methylated." (PMID 36585450, 2023). "Significant negative correlations were found in 10/10 HLA-A probes, 5/13 HLA-B probes, and 10/11 HLA-C probes in the tumor samples, and only 1/10, 3/13, and 2/11 for HLA-A, HLA-B, and HLA-C normal samples, respectively." (PMID 36050516, 2022). "Inferior outcome was explained by elements impairing T-cells’ recognition of tumor antigens on HLA-B." (PMID 35053465, 2022). "These immuno-scores, including TMB (tumor mutational burden), PD-L1, CTLA4, or immune-related genes (HLA-B, HLA-A, HLA-DRA), expand knowledge in tumor immune status and provide a potent prediction tool for the future." (PMID 36451642, 2022). "The average level of methylation was significantly higher in the tumor samples for all regions except the HLA-B promoter." (PMID 36050516, 2022). "We therefore subclassified our cohort according to the MSI/MMR status of tumor samples among patients heterozygous at the HLA-B gene (n = 71)." (PMID 34732240, 2021). "For effective killing of tumors, CD8+ T cells recognize tumor peptides presented by molecules of human leukocyte antigen class I. In humans, there are three major HLA-I genes (HLA-A, HLA-B, and HLA-C)." (PMID 33416081, 2021). "Compared to the normal tissue N1, all the PDXs, Org2, and the primary tumor showed a reduction of transcript abundance of the major histocompatibility complex (HLA-A and HLA-B) and of galectin-9, the main ligand of the inhibitory receptor Tim-3." (PMID 33602919, 2021). "The HLA-I expression type was determined by immunohistochemistry of HLA-A, HLA-B, HLA-C and β2-microglobulin in the centre of the tumour (CT) and in the invasive margin (IM) of samples from 293 patients (total loss vs. preserved type)." (PMID 32203213, 2020). "MHC class I family mainly includes HLA‐A, HLA‐B, and HLA‐C, essential for endogenous antigen presentation of tumor cells and subsequent recognition by the immune system." (PMID 33252851, 2020). "The class-I HLAs of patient 01 were typed as HLA-A*11:01, HLA-A*02:10, HLA-B*40:01, HLA-B*40:01, HLA-C*08:01, and HLA-C*07:02, which were double-checked by assaying tumor and blood samples." (PMID 33208106, 2020). "Priming experiments with a control peptide frequently presented on HLA-B*18 in both, tumor and benign tissues (peptide presentation > 90% in HLA-matched sources), confirmed MM-specificity of the induced T-cell responses." (PMID 32111817, 2020). "This suggests that tumor samples with a higher relative expression of HLA-B also had increased expression of inflammation and immune infiltration markers." (PMID 30833945, 2019). "Robust expression of MHC class I genes (HLA-A, HLA-B, and HLA-C) was seen in PA tumor and immune cells, suggesting that antigen presentation is intact." (PMID 31427603, 2019). "Proteins, HLAB, ADAMTS2, LTBP3, JAG2 and NME2 were significantly associated with tumor progression, vascular invasion and distant liver metastasis." (PMID 30679934, 2019). "Expression of HLAB, protein 14-3-3β, LTBP3, ADAMTS2, JAG2 and NME2 on tumour cells was significantly associated with clinical parameters related to tumour progression, invasion and metastasis." (PMID 30679934, 2019).